IGF1 (insulin like growth factor 1)
Diseases named in the same sentence as IGF1 in open-access papers (continued):
Sharing a sentence is not in itself a finding about the gene and the disease.
Hyperinsulinemia (continued). "In DM, hyperinsulinemia is observed, leading to an increase in IGF-1, which promotes the abnormal proliferation of hepatocytes." (PMID 40624408, 2025). "Mechanistically, hyperinsulinemia elevates insulin-like growth factor-1 (IGF-1) levels, a potent mitogen that promotes cellular proliferation and inhibits apoptosis, accelerating CRC progression." (PMID 40243559, 2025). "Hyperinsulinemia, through synergistic effect with LH, intensifies this process by directly stimulating ovarian granulosa and theca cells, and indirectly by insulin-like growth factor-1 (IGF-1)." (PMID 40564059, 2025). "Hyperinsulinemia induced IGF1 resistance, accompanied by reduced IGF1R protein, as well as Igf1r and Irs2 mRNA expression via over-activation of phosphoinositide 3-kinase/forkhead box O1 (PI3K-FOXO1) signaling." (PMID 40105689, 2025). "Hyperinsulinemia reduces the levels of insulin-like growth factor-binding proteins (IGFBPs), which normally sequester IGF-1, thereby increasing the bioavailability of IGF-1." (PMID 40428567, 2025). "Hyperinsulinemia also decreases the concentration of insulin-like growth factor-binding proteins (IGFBPs), increasing free insulin-like growth factor 1 (IGF-1) levels." (PMID 41375041, 2025). "In contrast, long-term consumption of a high glycemic load diet results in hyperinsulinemia, which in turn increases the bioavailability of insulin-like growth factor 1 and promotes EC." (PMID 41431696, 2025). "We found that hyperinsulinemia promoted hypothalamic neuronal IGF1 resistance, evidenced by reduced INSR and IGF1R protein levels in immortalized hypothalamic neurons, primary hypothalamic cultures, and human iPSC-derived hypothalamic neurons." (PMID 40105689, 2025). "Diets high in glycemic load and low in dietary fiber contribute to hyperinsulinemia, which can stimulate the insulin-like growth factor-1 (IGF-1) axis – a potent mitogenic and anti-apoptotic signaling pathway." (PMID 40901208, 2025). "Some researchers have also proposed, hyperinsulinemia and IGF‐1 can alter the cell cycle regulation via the RAS/MAPK/ERK pathway, thereby promoting the growth, differentiation, and proliferation of tumor cells." (PMID 40550558, 2025). "Hyperinsulinemia suppresses hepatic insulin-like growth factor binding protein-1 synthesis, increasing bioavailable IGF-1, which in turn acts synergistically with LH to enhance ovarian androgen production." (PMID 41384021, 2025). "This metabolic disruption leads to hyperinsulinemia and increased insulin‐like growth factor‐1 (IGF‐1) signaling, both of which drive tumor growth." (PMID 40387523, 2025). "A common consequence of an increased BMI is hyperinsulinemia, which also stimulates the expression of Insulin-like Growth Factor-1 (IGF-1)." (PMID 39940361, 2025). "One key factor is hyperinsulinemia and elevated levels of insulin-like growth factor 1 (IGF-1), which together stimulate the proliferation of tumor cells." (PMID 40843857, 2025). "High-calorie diets, particularly those rich in refined carbohydrates and saturated fats, lead to hyperinsulinemia and elevated circulating IGF-1 levels." (PMID 40428567, 2025). "Obese mares exhibited hyperinsulinemia along with reduced levels of albumin, albumin/globulin ratio, IGF-1, and glucose/insulin ratio." (PMID 40901060, 2025). "Many transcription factors such as FoxO1, 1,25-dihydroxyvitamin D and calcium are connected with sebum production, while hyperandrogenemia, hyperinsulinemia, and high levels of insulin growth factor-1 (IGF-1) play a role in acne development." (PMID 40806666, 2025). "Key components of MetS, such as hyperinsulinemia (via the IGF-1 signaling pathway), hyperglycemia, central obesity, and elevated body mass index (BMI), have demonstrated a strong link with increased cancer risk." (PMID 40572713, 2025).
Hyperinsulinemia (continued). "The findings of the present study align with accumulating evidence that hyperinsulinemia, IGF-1 signaling, and androgen excess constitute an interconnected triad in PCOS pathophysiology." (PMID 41384021, 2025). "Hyperinsulinemia with downstream IGF-1/IGF-1R signaling activates the PI3K–AKT–mTOR and MAPK pathways, supporting the survival and clonal expansion of mutated thyrocytes in the context of chronic low-grade inflammation." (PMID 41514562, 2025). "Human studies revealed increased cancer mortality in patients with hyperinsulinemia, elevated levels of IGF-1, or both factors." (PMID 38392069, 2024). "Mechanistic studies have shown that hyperinsulinemia increases the bioavailability of IGF1 (insulin-like growth factor 1) and up-regulates cancer-related signaling pathways such as the PI3K-AKT-MTOR pathway." (PMID 38319509, 2024). "Hyperinsulinemia stimulates the growth of various organs and tissues, most likely through overexpression of the receptor for insulin-like growth factor-1 (IGF-1)." (PMID 38768058, 2024). "Hyperinsulinemia and IR promote carcinogenesis via growth promoting and mitogenic effects of insulin and IGF-1." (PMID 39103728, 2024). "Hyperinsulinemia has also been associated with carcinogenesis; untreated type 2 diabetes may contribute to the risk of malignancy by stimulating the insulin receptors of cancer cells directly or indirectly by increasing the IGF1 levels with carcinogenic outcomes." (PMID 38664791, 2024). "These contrasting results underline the importance of further studies on the influence of a microenvironment characterised by hyperinsulinemia, also in combination with IGF-1 and hyperglycaemia, on BC cells proliferation and metastatic potentials." (PMID 39408212, 2024). "Increased levels of insulin-like growth factor 1 (IGF-1) induced by hyperinsulinemia act as a pro-mitogen, which decreases apoptosis in tumor cells." (PMID 38339127, 2024). "At the linear logistic regression, we found that IGF-1, HOMA-IR, and ALT/AST ratio were independently associated with a confirmed hyperinsulinism." (PMID 38920551, 2024). "At the multivariate analysis, IGF-1 levels over 203 ng/mL and HOMA-IR higher than 6.2 were respectively associated with a 9- and 18-times higher odds ratio for hyperinsulinism." (PMID 38920551, 2024). "The multivariate analysis highlighted that an IGF-1 level higher than 203 ng/mL and HOMA index higher than 6.2 are respectively associated with a 9-times and 18-times higher odds ratio for hyperinsulinism." (PMID 38920551, 2024). "At the linear logistic regression assessment, we found that insulin growth factor-1 (IGF-1), HOMA-IR, and ALT/AST ratio were independently associated with confirmed hyperinsulinism." (PMID 38920551, 2024). "Elevated levels of insulin and IGF-1 also affect cancer prognosis, with worse outcomes in patients with diabetes and hyperinsulinemia." (PMID 37233716, 2023). "Prolonged hyperinsulinemia raises the bioavailability of IGF-1, which has been shown to promote proliferation and inhibit apoptosis in normal prostate and tumor cells in vitro, increasing the risk of PCa." (PMID 36837490, 2023). "Hyperinsulinemia increases the biological activity of IGF-1, which induces and activates the Ras/Raf/MAPK and PI3K/Akt/mTOR pathways, thus reduces apoptosis promotes cell proliferation and survival, and increases the risk of tumor development." (PMID 37736725, 2023). "The role of insulin in mediating normal growth in healthy individuals and promoting adiposity during hyperinsulinemia through maintenance of the insulin–growth hormone (GH)–insulin-like growth factor 1 (IGF-1) axis is well recognized." (PMID 37246587, 2023). "Hyperinsulinemia has also been indicated to reduce IGFBPs production and increase IGF-1 biological activity, ultimately leading to cancer progression." (PMID 37373357, 2023).
Hyperinsulinemia (continued). "Further study into the synergistic effect of insulin and IGF-1 to investigate IGF-1 response in hyperinsulinemia conditions can help understand the correlation between metabolic dysregulation and the IGF axis in cancer progression." (PMID 37373357, 2023). "Hyperinsulinemia also intensifies insulin growth factor-1 (IGF-1)-stimulated and LH-stimulated androgen production." (PMID 37791160, 2023). "They showed the involvement of factors such as hyperglycemia, hyperinsulinemia, insulin-like growth factor 1 (IGF-1), oxidative stress, and sex hormones." (PMID 37033970, 2023). "Several factors such as adipokines, IGFs (IGF-1 as mitogens), dyslipidemia, hyperglycemia, hyperinsulinemia, and inflammatory cytokines link BC with obesity and diabetes." (PMID 36849958, 2023). "One of the predisposing biological agents for cancer incidence and its development is insulin-related disorders, particularly hyperinsulinemia, that play a crucial role in tumor development through insulin-like growth factor-1 (IGF-1)." (PMID 36617570, 2023). "Current evidence indicates that insulin and hyperinsulinemia promote the synthesis and biological activity of IGF-1 and IGF-2, which regulates the energy-dependent growth process." (PMID 37361533, 2023). "Metformin lowers the mitogenic activity of hyperinsulinemia through a reduction in systemic levels of insulin and insulin-like growth factor 1 (IGF-1) and displays an anti-neoplastic effect." (PMID 37834839, 2023). "Hyperinsulinemia elevates serum concentrations of free insulin-like growth factor-1 (IGF-1) and androgens, while simultaneously reducing insulin-like growth factor-binding protein 3 (IGFBP-3) and sex hormone-binding globulin." (PMID 36964104, 2023). "Hyperinsulinemia also stimulates insulin-like growth factor-1 (IGF) production in the liver and reduces circulating levels of IGF-binding proteins, culminating in increased plasma levels of IGF-1 and IGF-2, two growth factors that promote cell proliferation." (PMID 37364149, 2023). "In the conditional KrasG12D mouse model, mice with diet-induced obesity developed hyperinsulinemia, hyperglycemia, hyperleptinemia, and elevated levels of IGF-1." (PMID 36964133, 2023). "The bioavailability and expression of insulin-like growth factor-1 (IGF-1) are enhanced by hyperinsulinemia, consequently increasing cell proliferation and reducing apoptosis." (PMID 38082394, 2023). "In women, additional mechanisms involving the direct actions of GH and IGF-1 on adrenal and ovarian androgen production, as well as hyperandrogenism due to GH mediated-hyperinsulinism, have been proposed." (PMID 36721176, 2023). "Hyperinsulinemia leads to increased levels of insulin-like growth factor 1 that acts as an antiapoptotic and growth factor on colonic mucosa, stimulating tumor cell proliferation." (PMID 35223684, 2022). "The reduced tissue sensitivity to insulin resulted in an increase in glucose and insulin levels, and chronic hyperinsulinemia promoted the secretion of insulin-like growth factor 1 (IGF-1) and a decrease in the production of IGF-binding proteins." (PMID 35409299, 2022). "Prepubertal fast growth seems to be dependent on the increased bioavailability of IGF-1 as a result of hyperinsulinemia and on the skeletal growth-promoting effect of increased leptin levels on chondrocyte proliferation and maturation." (PMID 36263328, 2022). "Research has shown that hyperinsulinemia and elevated insulin-like growth factor-1 in patients with type 2 diabetes are closely related to malignant tumors." (PMID 35872697, 2022). "In type 2 diabetes, the possible mechanisms contributing to gallbladder cancer include: Hyperinsulinemia and up-regulation of insulin-like growth factor-1 (IGF-1) levels promote cell proliferation and inhibit apoptosis." (PMID 35907868, 2022). "It has been elucidated that hyperinsulinemia can promote the synthesis and biological activity of IGF-1." (PMID 35873545, 2022).
Hyperinsulinemia (continued). "Hyperinsulinemia and the resulting increase in insulin-like growth factor-1, which plays an important role in tumorigenesis, have also been suggested as the main mechanism." (PMID 36618838, 2022). "As a result, hyperinsulinemia produces and releases large amounts of IGF-1 from the liver and exerts growth factor-like activity on hepatocytes." (PMID 35873545, 2022). "Metabolic alteration has also been found in obese cancer patients including hyperinsulinemia and elevated serum level of IGF-1." (PMID 35816477, 2022). "Studies in mammals showed that the glucose level (hyperglycemia and hyperinsulinemia) and the insulin/insulin-like growth factor 1 (IGF-1) pathway-related molecules, play an essential role in aging." (PMID 35892977, 2022). "It is known that hyperinsulinemia, a characteristic that was observed in our sample, induces a higher production of IGF-1 and lower production of IGFBP-1 (Insulin-like growth factor-binding protein 1) by the liver." (PMID 35703718, 2022). "Hyperinsulinemia has been suggested to be involved in carcinogenesis directly by promoting cancer initiation and progression, and indirectly through IGF‐1." (PMID 36262540, 2022). "Hyperinsulinemia increases the circulating levels of insulin-like growth factor 1 (IGF1) and thus inhibits apoptosis and favors cell division." (PMID 33802047, 2021). "As mentioned, hyperinsulinemia leads to an increase in IGF-1 bioactivity through inhibition of IGFBP-1 and IGFBP-2." (PMID 34208601, 2021). "Potential factors affecting pancreatic ductal proliferation pathways and apoptosis include hyperglycemia, hyperinsulinemia, and the increased expression of insulin-like growth factor 1 (IGF-1)." (PMID 34830745, 2021). "Although total IGF-1 levels in the blood are lowered in obese people, the concentration of its free fraction is elevated, possibly due to hyperinsulinemia." (PMID 34208601, 2021). "High insulin levels (hyperinsulinemia) affect cancer development by directly stimulating the insulin receptor (IR) and/or indirectly through increasing the level of circulating Insulin Like Growth Factor 1 (IGF-1)." (PMID 33673109, 2021). "Hyperinsulinemia, which can contribute to common defects in insulin/IGF-1 pathways on the pancreatic periphery and in the pancreatic islet β-cell, is considered a key causative factor for the development of DM II." (PMID 34208601, 2021). "On a mouse model with liver-specific igf-1 gene deletion (LID model), very low concentrations of cIGF-1, high concentrations of GH and hyperinsulinemia were observed, associated with muscle insulin insensitivity." (PMID 34208601, 2021). "The direct effect of metformin includes AMPK-dependent and AMPK-independent effects, while glucose levels decrease, hyperinsulinemia and an increase in IGF-1 levels are considered as indirect." (PMID 34208601, 2021). "In MC4R knock-out mice, to the contrary, GH and IGF-1 suppression was observed recovered when hyperphagia was prevented and hyperinsulinemia reversed." (PMID 34177811, 2021). "iLIRKO mice displayed hyperinsulinemia and increased beta cell mass, suggesting a liver–pancreas endocrine axis in which IGF-1 functions as a liver derived growth factor to promote compensatory pancreatic islet hyperplasia through IRA." (PMID 34440804, 2021). "Among these factors are the severity of hyperinsulinemia and HA, the blood levels of the binding proteins for insulin, IGF-1 (IGFBP-1) and androgens (SHBG), and the blood levels of AMH and HDL-C." (PMID 33429918, 2021). "During cancer progression and metastasis, insulin and IGF-1 have a functional role, especially in patients with hyperinsulinemia." (PMID 34638601, 2021). "First, chronic exposure to hyperinsulinemia plays an important role in tumor development and progression by modulating insulin-like growth factor-1 (IGF-1) activity." (PMID 34638244, 2021).
Hyperinsulinemia (continued). "At the same time, hyperglycemia directly promotes hyperinsulinemia and induces tumorigenesis by indirectly increasing IGF-1 function." (PMID 33468224, 2021). "An indirect action on tumor cells is related to metformin glucose lowering effect, reduction of hyperinsulinemia, insulin-like growth factor-1 (IGF-1) and IR." (PMID 33562458, 2021). "Hyperinsulinemia augments growth hormone receptor signalling, and increases hepatic IGF-1 production." (PMID 33816477, 2021). "Excessive FFAs tend to be stored in non-adipose organs such as the pancreas and others (liver, muscle, heart, and kidney), promoting fatty pancreas disease, insulin resistance, hyperinsulinemia, and diabetes accompanied by increased levels of insulin and IGF1." (PMID 33668583, 2021). "Although GH levels are reduced in obesity, hyperinsulinemia raises density and sensitivity of hepatic GH-receptors in diabetic and obese patients, leading to overproduction of IGF-1 and increasing its availability by decreasing IGFBP-1 levels." (PMID 34205356, 2021). "Hyperinsulinemia increases the serum level of free IGF–1 and decreases the serum level of insulin-like growth factor binding protein (IGFBP)–3." (PMID 33143702, 2020). "Suppressed serum IGFBP-1 and increased free IGF-1 have been observed in chronic or short-term hyperinsulinemia." (PMID 33008076, 2020). "Hyperinsulinemia and increased IGF-1 levels directly result in the growth of epithelial and fibroblastic cells via receptor activation." (PMID 33143702, 2020). "High consumption of refined carbohydrates can lead to hyperinsulinemia followed by the activation of the insulin like growth factor (IGF)-1 axis and inflammatory pathways." (PMID 31705265, 2020). "In vitro and animal studies, suggested elevated levels of insulin-like growth factor-1 (IGF-1) induced by hyperinsulinemia to be the main factor in cancer development and progression." (PMID 32907593, 2020). "In pathological conditions of hyperinsulinemia, insulin can trigger the proliferation pathway activated by IGF-1 in kidney cancer cells lines." (PMID 33008076, 2020). "We believe that the role of IGF-R activation is more important than the increase in serum IGF-1 level and hyperinsulinemia in the acrochordon development process." (PMID 33143702, 2020). "Hyperinsulinemia reduces the production of insulin-like growth factor (IGF) binding protein and results in the increase of bioavailable IGF-1." (PMID 32393273, 2020). "Laboratory investigations, executed during HY (glucose value 42 mg/dL), showed hyperinsulinism (20,1 μUI/ml), while ammonium, lactic acid, cortisol, IGF-1, plasmatic aminoacids, acylcarnitines and urinary organic acids profiles were normal." (PMID 32928245, 2020). "Hyperglycemia or hyperinsulinemia tends to modulate the over-secretion of free IGF-1, that leads to IGF-1Rs activation and resulting increased proliferation, invasive binding and cellular metastasis." (PMID 30705329, 2019). "On the other hand, hyperinsulinemia is highly associated with the amount of insulin-like growth factor 1 (IGF-1) locally, thus, excess IGF-1 in tumor cells." (PMID 31398937, 2019). "Hyperinsulinemia also stimulates thyroid hormone production and secretion, and IGF-1 levels elevate in the thyroid gland, possibly as a result of elevated GH." (PMID 31080828, 2019). "For instance, a decrease in IGFBP1 production leads to a reduction in IGF-1 levels, and it is capable of inducing hyperinsulinemia and abnormal glucose clearance." (PMID 31601230, 2019). "Hyperinsulinemia along with hyperandrogenemia and enhanced levels of IGF-1 inhibit sex hormone-binding globulin secretion, which surges the levels of bioactive androgens and worsens the clinical manifestations of androgen excess in PCOS patients." (PMID 31970309, 2019).